SOX10 (SRY-box transcription factor 10)
Diseases named in the same sentence as SOX10 in open-access papers (continued):
Sharing a sentence is not in itself a finding about the gene and the disease.
peripheral demyelinating neuropathy (17 papers, 2008 to 2025). "Peripheral demyelinating neuropathy and central dysmyelination, as symptoms in patients with SOX10 mutations, underscore the relevance of SOX10 for myelinating glia, including oligodendroglial cells." (PMID 39769160, 2024). "Finally, mutations in SOX10 target genes including those encoding peripheral myelin protein 22 (PMP22), myelin protein zero (MPZ), and gap junction beta 1 (GJB1) cause demyelinating peripheral neuropathy." (PMID 27821050, 2016). "Mutations in MPZ, SOX10, and EGR2 have been implicated in demyelinating peripheral neuropathies, suggesting that components of this transcriptional network are candidates for harboring disease-causing mutations (or otherwise functional variants) that affect MPZ expression." (PMID 21179557, 2010).
schizophrenia (15 papers, 2009 to 2024). A major psychotic disorder characterized by abnormalities in the perception or expression of reality. "Another gene encoding a myeline component, SOX10, is located in a major susceptibility locus for schizophrenia." (PMID 39061389, 2024). "DNA methylation and gene expression studies also showed differences in PFC of schizophrenia patients and healthy controls in genes related to astrocyte-associated functional pathways and oligodendrocyte development and myelination i.e., SOX10." (PMID 36833173, 2023). "Another gene, SOX10, which encodes a crucial transcription factor for oligodendrocyte differentiation, has also been shown to have reduced expression in postmortem schizophrenia patients that was correlated with hypermethylation." (PMID 32764320, 2020). "These include NOS1, AKT1, DTNBP1, DNMT1, PPP3CC and SOX10, which have previously been associated with schizophrenia." (PMID 24399042, 2014). "Interestingly, the CpG island within the promoter region of SOX10 is hypermethylated in brains of patients with schizophrenia, which is directly associated with a decreased expression of SOX10 and other OL-related genes." (PMID 31614602, 2019). "The SOX10 gene was also highly methylated in the PFC of patients with schizophrenia, pointing to oligodendrocyte dysfunction in schizophrenia." (PMID 36833173, 2023). "Significant down-regulation of SOX9 expression has been revealed in neural progenitors derived from Fragile X Syndrome ESCs while downregulation of SOX10 expression is detected in brains of patients with schizophrenia." (PMID 33867936, 2021). "The resultant under expression of SOX10 then leads to the dysfunction of the oligodendrocytes with the key oligodendrocyte and myelination genes being down-regulated has been reported in schizophrenia patients." (PMID 34831111, 2021). "Iwamoto and colleagues reported the hypermethylation of SOX10 in the brain of schizophrenia patients and also found that the hypermethylation was correlated to the under expression of SOX10." (PMID 34831111, 2021). "Studies using post-mortem brains of schizophrenia patients have reported that the under-expression of SOX10 can lead to the dysfunction of oligodendrocytes with the downregulation of the important oligodendrocyte and myelination gene." (PMID 34831111, 2021). "Some of the genes with differential methylation were previously reported to be associated with schizophrenia, such as AKT1, NOS1, DNMT1, PPP3CC, DTNBP1, and SOX10." (PMID 32764320, 2020). "We also found DNMT1, NOS1 and SOX10 to be differentially methylated in brain tissue from patients with schizophrenia." (PMID 24399042, 2014). "Also, dysfunction of oligodendrocytes in patients with schizophrenia was correlated with increased DNA methylation of SOX10 gene." (PMID 33867936, 2021). "Therefore, the CpG DNA methylation status of SOX10 gene is proposed as an epigenetic sign of oligodendrocyte dysfunction in schizophrenia patients." (PMID 34831111, 2021). "Notably, previous studies reported an aberrant increase of the repressor TF ID4 in schizophrenia patient brains and reduction of the OL-specific activator TF SOX10 in the brains of schizophrenia, bipolar, and major depression postmortem cohorts." (PMID 29249816, 2017). "The presumption that Sox10 could influence GSN expression is additionally supported by the fact that in patients with schizophrenia the SOX10 methylation level was inversely correlated with the expression level of several “oligodendrocyte” genes including GSN." (PMID 25352156, 2016). "Consistent with our findings, reduced SOX10 expression was found in the hippocampus and anterior cingulate cortex (ACC) of subjects with schizophrenia." (PMID 32714147, 2020). "Three schizophrenia-unique genes related to glial cell differentiation were identified: ERBB3, PTPRZ1, and SOX10." (PMID 32398742, 2020).
schizophrenia (continued). "Seven genes, APP, ERBB3, FEZ1, HSPA2, SERPINI1, SOX10 and SYN2, display altered expression in studies of schizophrenia or bipolar disorder." (PMID 19300510, 2009). "In qRT-PCR, SOX10, L-MAG/T-MAG, and Tf transcript levels were reduced by over three folds, one fold, and two folds, respectively, in the mPFC, an observation consistent with hypoactivity of executive-control in schizophrenia." (PMID 32714147, 2020). "For instance hyper- DNA methylation of RELN, SOX10 [SRY (sex determining region Y)-box 10], FOXP2 (forkhead box P2), and HTR2A as well as hypo- DNA methylation of MB-COMT (membrane-bound catechol-O-methyltransferase) and HTR2A have been reported in schizophrenia." (PMID 25206360, 2014).
Kallmann syndrome (14 papers, 2013 to 2025). Kallmann syndrome (KS) is a developmental genetic disorder characterized by the association of congenital hypogonadotropic hypogonadism (CHH) due to gonadotropin-releasing hormone (GnRH) deficiency, and anosmia or hyposmia (with hypoplasia or aplasia of the olfactory bulbs). "Several individuals with SOX10-associated Kallmann syndrome exhibit altered thyroid function and reduced bone mineral density." (PMID 39791977, 2025). "One case was identified as co-existence of WS2 and Kallmann syndrome associated with SOX10 gene variants." (PMID 38659011, 2024). "The SOX10 c.481C>T (p.R161C) mutation has been previously reported in a Caucasian patient with Kallmann syndrome that features congenital hypogonadotropic hypogonadism with anosmia." (PMID 32908489, 2020). "Of these, the c.481C>T (p.R161C) variant in SOX10 has been previously reported resulting in Kallmann syndrome in a Caucasian patient." (PMID 32908489, 2020). "Loss‐of‐function SOX10 mutations are found in roughly one‐third of cases of Kallmann's syndrome (combined anosmia and hypogonadotropic hypogonadism) with deafness." (PMID 30134068, 2018). "Our data suggest that human Sox10 mutations cause Kallmann's syndrome by disrupting the differentiation of OECs, which promote embryonic olfactory axon targeting and hence olfactory receptor neuron maturation, and GnRH neuron migration to the forebrain." (PMID 23862023, 2013). "Recently, spontaneous mutations in the transcription factor gene Sox10 were associated with Kallmann's syndrome phenotypes: anosmia, hypogonadism and cryptorchidism." (PMID 23862023, 2013). "Therefore, SOX10 appeared to be a likely candidate mutation to explain the presence of anosmia within the disease spectrum." (PMID 38132479, 2023). "A total of 181 SOX10 mutations have been described in patients with WS and/or Kallmann syndrome (KS), of which 55% are truncating mutations (nonsense, frameshift, and splicing defect) and null alleles (gross rearrangement or deletion), while the remainder represent missense variants." (PMID 33362852, 2020). "Despite the fact that SOX10 c.481C>T (p.R161C) mutation was previously associated with Kallmann syndrome, family members with this mutation in our study had either normal or only WS2 (hearing loss and hair hypopigmentation) phenotype, indicating a rather variable clinical manifestation." (PMID 32908489, 2020). "Sox10 mutations have been associated with Kallmann's syndrome phenotypes, but their effect on olfactory system development is unknown." (PMID 23862023, 2013). "The team then created a SOX10 knockout mouse model and found that they exhibited a massive loss of olfactory ensheathing cells that hindered the migration signals of olfactory and GnRH neurons, causing characteristic clinical manifestations of KS such as anosmia and hypogonadism." (PMID 33597923, 2020). "However, it remains unknown if there is a specific genotype-phenotype correlation between certain SOX10 mutations and Kallmann syndrome." (PMID 32908489, 2020). "Here, we test the hypothesis arising from the association of Sox10 mutations with Kallmann's syndrome, namely that Sox10 is required for OEC differentiation and that OECs are required for the entry of olfactory axons and GnRH neurons into the embryonic forebrain." (PMID 23862023, 2013). "Mutations in SOX10 have been associated with congenital disorders such as Waardenburg–Shah Syndrome, PCWH syndrome, and Kallman syndrome, underscoring its clinical significance." (PMID 38132479, 2023). "The diversity and overlap of clinical features in patients with Waardenburg–Shah syndrome, PCWH, and Kallman syndrome underscore the role of SOX10 as a common factor for pathogenesis." (PMID 38132479, 2023). "The same SOX10 c.481C>T (p.R161C) mutation has previously been reported in a Caucasian patient with Kallmann syndrome, in whom the presence or absence of hearing loss and pigmentation defect was not described." (PMID 32908489, 2020).
Kallmann syndrome (continued). "It was molecularly proven in 25 (8 CHD7 mutations, 6 FGFR1 mutations, 7 ANOS1 mutations, 2 PROKR2 mutations, 1 digenic SOX10/SEMA3F mutation, and 1 digenic ROBO3/IGFS10 mutation with anosmia and later absent puberty)." (PMID 40193582, 2025).
glioblastoma (13 papers, 2019 to 2025). The most malignant astrocytic tumor (WHO grade IV). "We show that low SOX10 expression is linked to neural stem-cell (NSC)-like glioblastoma cell states and is a consequence of temozolomide treatment in animal and cell line models." (PMID 39285246, 2024). "Here, we used scRNA-seq analysis to map SOX10-dependent cell states in a syngeneic mouse glioblastoma model that reflects essential aspects of therapy-associated human tumor progression, including the emergence of a quiescent stem cell state." (PMID 39285246, 2024). "Repression of the RTK I MR SOX10 in human glioblastoma cell lines caused a subtype transition to a mesenchymal cellular state via the remodelling of active enhancers." (PMID 33339831, 2020). "Notably, SOX10 overexpression has been linked to poorer overall survival in glioblastoma patients and unfavourable prognosis." (PMID 40159622, 2025). "Collectively, our in vitro analysis indicates that SOX10 suppression by genetic knockdown or TMZ treatment transitioned human and mouse glioblastoma to a qNSC-like cell state, supporting the use of SOX10-KD as an in vitro model for therapy-associated phenotypic transition in glioblastoma." (PMID 39285246, 2024). "Interestingly, hypermethylation of the SOX10 promoter was found to be associated with shorter survival rates in glioblastoma." (PMID 30961526, 2019). "Recently, we found AC-like cell states enriched in glioblastoma patient tumors with low expression of the oligodendrocyte lineage factor driver SRY-Box Transcription Factor 10 (SOX10)." (PMID 40611337, 2025). "The present study sought to investigate the mechanisms by which SOX10 influences tumour proliferation following boric acid treatment, as well as its role in ferroptosis and glioblastoma progression." (PMID 40159622, 2025). "The upregulation of the NSC-like glioblastoma marker Sox9 in Sox10-KD tumors was confirmed at the protein level by immunohistochemical analysis." (PMID 39285246, 2024). "We next postulated that Sox10-KD leads to comparable cell-state transitions in glioblastoma cell lines, allowing us to use Sox10-KD cells as in vitro models to evaluate therapeutic strategies for targeting the quiescent/slow-cycling state." (PMID 39285246, 2024). "In summary, SOX10 suppression mediates glioblastoma progression through NSC/developmental cell-state transition, including the induction of a targetable quiescent NSC state." (PMID 39285246, 2024). "We previously showed that suppressing the oligodendrocyte-lineage regulator SOX10 promotes glioblastoma progression." (PMID 39285246, 2024). "This study examines SOX10-dependent cell-state transitions in glioblastoma and uses single-cell analyses to design a combination therapy that extends survival in an immunocompetent glioblastoma mouse model." (PMID 39285246, 2024). "Here, we showed that SOX10 governs glioblastoma plasticity by mediating the transition between two clinically relevant cell states." (PMID 39285246, 2024). "We confirmed TMZ-induced SOX10 suppression in the human glioblastoma cell lines cultivated in 2D-adherent culture or in co-culture with iPSC-derived cerebral organoids (Fig. EV1A,B)." (PMID 39285246, 2024). "Here, we analyze SOX10-mediated phenotypic plasticity and exploit it for glioblastoma therapy design." (PMID 39285246, 2024). "In the current study, we found SOX10 expression to be regulated by DNA methylation, which is in line with a recent study where SOX10– glioblastoma cells also harbored features that are more aggressive and a mesenchymal phenotype." (PMID 36040798, 2022). "Although at lower levels, the majority of oligodendrogliomas and a significant proportion of astrocytomas, including glioblastomas, produced SOX10." (PMID 36142793, 2022). "In fact, mutant SOX10 proteins surprisingly outcompete wildtype SOX10 for DNA binding when co-expressed in glioblastoma cells." (PMID 36003149, 2022).
glioblastoma (continued). "This evidence of its involvement in clinically relevant state transitions makes SOX10 a particularly interesting candidate to study epigenetic control and remodelling of subtype gene regulation in glioblastoma." (PMID 33339831, 2020). "SOX10 repression in an in vivo syngeneic graft glioblastoma mouse model results in increased tumour invasion, immune cell infiltration and significantly reduced survival, reminiscent of progressive human glioblastoma." (PMID 33339831, 2020). "Furthermore, Sox10 suppression by genetic knockdown resulted in the transition to an AC-like cell state in mouse glioblastoma cells in vitro." (PMID 40611337, 2025). "Specifically, the study aimed to evaluate whether boric acid treatment in U87 glioblastoma cells could serve as a potential therapeutic strategy for glioblastoma by targeting the SOX10/GPx4/ACSL4 signalling axis." (PMID 40159622, 2025). "Finally, we tested the efficacy of our combination therapy in vivo using our Sox10-KD glioblastoma syngeneic mouse model." (PMID 39285246, 2024). "Therefore, we analyzed the correlation of SOX10 expression levels and glioblastoma cell state in 324 primary IDH-WT glioblastoma of the TCGA-GBM dataset." (PMID 39285246, 2024). "Given the role of SOX10 in the differentiation of neural stem and progenitor cells, we hypothesized that SOX10 is a key factor determining glioblastoma cell state." (PMID 39285246, 2024). "In addition, TMZ-dependent Sox10 downregulation also was observed in a glioblastoma animal model (Fig. EV1D)." (PMID 39285246, 2024). "SOX10 repression remodels the glioblastoma enhancer landscape and promote MT process." (PMID 35851726, 2022). "Additionally, our transplantation models have been recently used to study the role of the SOX10 master regulator transcription factor in the determination of glioblastoma transcriptional and phenotypic transitions." (PMID 33435218, 2021). "Our subtype MR analysis identifies many candidates beyond SOX10 that are known to play roles in CNS development, suggesting a model in which MR activity maintains and interacts with genetic and epigenetic factors to define a glioblastoma cell state." (PMID 33339831, 2020). "In addition, the RTK I and MES tumour patients of our study cohort showed significantly different patients’ survival, and low SOX10 expression in MES-subtype glioblastoma of the TCGA cohort significantly correlated with adverse prognosis." (PMID 33339831, 2020). "Furthermore, we showed that temozolomide treatment suppressed SOX10 in glioblastoma model systems, resulting in the enrichment of a slow-cycling SOX9/p27 double-positive cell population, suggesting a role for SOX10-dependent cell-state transitions in therapy-associated tumor progression." (PMID 39285246, 2024). "The Western blot analysis of SOX10 and Nanog in NC-treated and Si-CD81-treated U118 cells indicated that knocking down CD81 weakened the stemness of glioblastoma cells." (PMID 35936722, 2022). "Our in vivo results suggest that loss of SOX10, leading to changes in myeloid cells, may be the underlying cause of this decrease in survival, an interpretation consistent with the correlation of low SOX10 expression and adverse survival that we observed for human MES-type glioblastoma patients." (PMID 33339831, 2020). "To test whether SOX10 repression is sufficient to induce OLC-like to NSC-like cell-state transitions, we turned to a syngeneic mouse glioblastoma model, wherein Sox10-high mouse glioblastoma (mGB1) neurospheres were transplanted in immunocompetent mice." (PMID 39285246, 2024).
glioblastoma (continued). "We tested this hypothesis by knocking down Sox10 and analyzing CGI methylation, showing that SOX10 suppression in the mouse glioblastoma cell line mGB1 indeed resulted in RTK2-CIMP-like DNA hypermethylation (Wilcoxon test, P < 2.2e − 16) and the OPC-to-AC-like cell state transition." (PMID 40611337, 2025). "Recently, we identified SOX10 (SRY-Box Transcription Factor 10), which specifies oligodendrocytic lineage differentiation during normal NSC development, as a master regulator of the RTK1-subtype of glioblastoma, and demonstrated that SOX10 suppression promotes tumor progression." (PMID 39285246, 2024). "Furthermore, SOX2 showed strong H3K27ac activation in all glioblastoma subtypes, and its RNA expression did not significantly change in the SOX10 knockdown models." (PMID 33339831, 2020). "Furthermore, analogous to the Sox10-KD conditions, a distinct, though statistically not significant, sensitization to Fimepinostat antiproliferative treatment was observed in TMZ-treated human glioblastoma control cells (Fig. EV4D)." (PMID 39285246, 2024).